ARID1A (AT-rich interaction domain 1A)
Diseases named in the same sentence as ARID1A in open-access papers (continued):
Sharing a sentence is not in itself a finding about the gene and the disease.
melanoma (continued). "However, ARID1A mutated tumors revealed UV-induced mutation signatures, showing a higher frequency of C>T substitutions in comparison with ARID1A wild-type melanomas." (PMID 36890819, 2023). "More interestingly, our analysis in Melanoma Cohort suggested that receiving PD-1 blockade (nivolumab) resulted in elevated Th17 infiltration, which encouraged us to uncover the linkage between ARID1A mutation and response to PD-1 inhibitor." (PMID 36369379, 2023). "An analysis of mutational patterns of ARID1A mutated melanomas (n = 116) versus ARID1A wild-type melanomas (n = 1180) revealed a significantly higher number of mutations in ARID1A mutated melanomas (mean 19.6 mutations versus 3.3 mutations per sample) (p < 0.0001)." (PMID 35565222, 2022). "Melanoma patients who had tumors with high levels of wild type ARID1A expression were found to have better responses to immune checkpoint inhibitors while patients with tumors having mutations in ARID1A had a poorer response." (PMID 35323214, 2022). "Notably, SMARCA4 mutations were slightly more common than ARID1A mutations in cases of non-small cell lung cancer, cervical cancer, and melanoma." (PMID 36371186, 2022). "Mutations in ARID1A have also been associated with melanoma metastasis to the brain." (PMID 35323214, 2022). "On the other hand, several studies suggest that overexpression of the wild-type of ARID1A in patients with melanoma is more responsive to immune checkpoint inhibitors, while patients with loss of ARID1A may have therapeutic implications by modulating response to immunotherapy." (PMID 36844227, 2023). "Interestingly, ARID1A mutations were detected more frequently on the head and extremities, compared to the trunk, and ARID1A-truncating mutations were associated with later stages of melanoma progression, correlating with an increase in the expression of an EZH2 transcriptional program." (PMID 35323214, 2022). "Nevi most often harbored canonical MAPK-pathway mutations in BRAF and NRAS, as well as in GRIN2A, while melanomas, along with BRAF and NRAS, frequently carried additional driver alterations in ARID1A, ARID2, CDKN2A, and PTEN." (PMID 41516405, 2026). "We explored early signaling responses to BRAF and MAPK inhibition in a BRAFV600E-sensitive melanoma cell line and a drug-resistant ARID1A-knockout (KO) derivative." (PMID 41708984, 2026). "Based on this study, ARID1A is the third most frequently mutated SWI/SNF, present in 9% of melanoma tumors in the TCGA database and associated with late-stage melanoma and metastasis to the brain." (PMID 36844227, 2023). "We believe if a strong benefit of ARID1A mutant samples to immune-checkpoint inhibitors was present in melanoma, our study would have detected it." (PMID 35565222, 2022). "The unique functions of ARID2 compared to the other ARIDs (ARID1A and ARID1B) will increase understanding of why ARID2 is more frequently mutated in melanoma." (PMID 35323214, 2022). "Within the group of ARID1A mutated melanomas, the mutational pattern with NF1 mutated melanomas harboring the greatest mutational load." (PMID 35565222, 2022). "The clinical origin and genetic data of ARID1A mutant melanoma argue that these tumors arise almost exclusively in UV-exposed sites and are rare in non-UV-exposed subtypes including mucosal, acral and uveal melanomas." (PMID 35565222, 2022). "The described pattern of NF1 mutant melanoma having the largest number of mutations within the three main subtypes of BRAF, NRAS, or NF1-mutated melanomas was apparent in our ARID1A mutated cohort." (PMID 35565222, 2022). "ARID1A variants (P650S, P1568S, L2119S, P1562L, G831A, G423E4) and ARID2 variants (D239N, S1489L, P1022S, S297F) were detected in 4 intracerebral melanoma tissues." (PMID 33578810, 2021). "Another recent analysis of human melanoma found that 21.4% of this tumor type has at least one HRD gene mutation including BRCA1, ARID1A, ATM, ATR and FANCA." (PMID 34885093, 2021).
melanoma (continued). "Second, the limited impact of ARID1A knockdown on the Q/R site in melanoma cell lines could be attributed to the already high editing levels in the Scramble group of these cell lines." (PMID 38835016, 2024). "Loss-of-function mutations in the components of the SWI/SNF complex such as AT-rich interactive domain-containing protein 1A (ARID1A), ARID1B, ARID2, or SMARCA4 are common in melanoma, suggesting that altered chromatin remodeling plays a role in the pathogenesis of this disease." (PMID 36844227, 2023). "Since 10.67% of melanoma patients have altered ARID1A, this may be useful in identifying ARID1B as a potential therapeutic target in patients with ARID1A loss or alteration." (PMID 36844227, 2023). "AT-Rich Interaction Domain 1A (ARID1A) is one of the genes most commonly mutated in melanoma without presenting a mutation hotspot (i.e., V600 in BRAF)." (PMID 35565222, 2022). "Upon further analysis, ARID1A mutated melanoma patients receiving their first non-adjuvant systemic therapy (with either targeted therapies or immune-checkpoint inhibitors) (n = 37)." (PMID 35565222, 2022). "However, a meta-analysis of mucosal melanomas suggests that copy number losses in ARID1B (33.3%) occur more frequently than in ARID1A (8.3%) for this melanoma sub-type." (PMID 35323214, 2022). "Larger prospective studies are warranted, however, our data assessing the largest cohort of ARID1A mutated melanoma presented to date does not support ARID1A mutations being a biomarker of response to immunotherapies in melanoma." (PMID 35565222, 2022). "The reason for the observed male predominance in our study of ARID1A mutated melanoma is currently not apparent to us." (PMID 35565222, 2022). "The remaining samples in which ARID1A mutations were detected were melanomas without known primary origin." (PMID 35565222, 2022). "Although there have not been any functional studies of ARID1B in melanoma, other cancer cells with mutations in ARID1A are highly vulnerable to ARID1B loss." (PMID 35323214, 2022). "In contrast to findings in other tumors, our data does not support ARID1A mutations being a biomarker of favorable response to immunotherapies in melanoma." (PMID 35565222, 2022). "No survival advantage of ARID1A mutated melanoma is apparent comparing survival data with the most recently published data on ICI in the CheckMate 067 study." (PMID 35565222, 2022). "Loss-of-function mutations in the SWI/SNF complex components such as AT-rich interactive domain-containing protein 1A (ARID1A), ARID1B, ARID2, or SMARCA4 are frequent in melanoma, suggesting that altered chromatin remodeling plays a role in the pathogenesis of this disease." (PMID 34440824, 2021). "Likewise, IS score, derived from 105 genes based on response to anti-CTLA-4 treatment in melanoma patients, was lower in the ARID1A-low group." (PMID 32878261, 2020). "Others have shown that combination inhibition of BRD4 and ATR demonstrates synergistic cytotoxic activity in other cancers such as lymphomas, melanoma and high-grade serous ovarian cancer 58–60, however ARID1A loss as a biomarker of sensitivity was not explored." (PMID 37841875, 2023). "However, a recent cohort study showed that ARID1A mutations do not have a major impact on survival and particularly on immune checkpoint inhibitors in melanoma." (PMID 36844227, 2023). "Not much was known about the role of ARID1A mutations in melanoma to date." (PMID 35565222, 2022). "This argues determining ARID1A mutation status in melanoma is currently not relevant for treatment." (PMID 35565222, 2022).
melanoma (continued). "However, the clinical significance of ARID1A mutations, especially in melanoma, remains undefined due to a lack of studies." (PMID 35565222, 2022). "In our analysis, alterations in genes regulating the SWI/SNF chromatin remodeling complex (LoF ARID2, LoF ARID1A, and SMARCA4) were most frequent in Class 3 melanomas." (PMID 38275886, 2024). "It will be important to elucidate the functions of ARID1A and ARID1B both during melanocyte development and in melanoma models, and to elucidate how they regulate enhancer function to regulate gene expression." (PMID 35323214, 2022). "As of yet, there have not been any studies investigating genomic occupancy of ARID1A/B in melanocytes and melanoma nor their role in melanocyte development or differentiation." (PMID 35323214, 2022). "ARID1A is a SWI/SNF family member and potential tumor suppressor in melanoma." (PMID 26405815, 2015). "Interestingly, we identified variants in five new candidate genes, i.e., ARID1A, ARID2, SMARCA4, PIK3R1 and BAP1, which neither have been previously identified in melanoma BM nor reported in CNS metastases from other cancers." (PMID 33578810, 2021). "Moreover, we detected single nucleotide transitions in ARID1A, ARID2, SMARCA4 and BAP1, all genes which have not been associated before with CNS metastases of melanomas." (PMID 33578810, 2021).
neuroblastoma (29 papers, 2013 to 2025). Neuroblastoma (NB) is the most common solid, extracranial childhood tumor. "Silencing of ARID1A/B caused a strong decrease in cyclin D1 protein levels in neuroblastoma cells, with a concomitant reduction in Rb phosphorylation." (PMID 36057593, 2022). "ARID1A loss is known to promote neuroblastoma growth and resistance in vivo, and ARID1B alterations are also predictive of poorer patient outcome." (PMID 34064704, 2021). "ARID1A recurrent mutations exhibit a broad tumor distribution, with particularly high prevalence in endometrioid and clear-cell ovarian cancers, gastric cancer, bladder cancer and neuroblastomas(~6%)." (PMID 41001036, 2025). "The recent report that loss of the tumor suppressor gene ARID1A causes de- differentiation of neuroblastoma cells supports this hypothesis." (PMID 38095019, 2023). "ARID1A mutations in neuroblastoma are associated with a strongly reduced overall survival." (PMID 37402719, 2023). "Moreover, ARID1A loss has functional driving effects on the oncogenic functions of neuroblastoma cells, including invasiveness and adrenergic-to-mesenchymal transition." (PMID 36057593, 2022). "Indeed, proliferative dependency on ARID1B in ARID1A-mutated neuroblastoma cell lines has already been demonstrated in one of these studies." (PMID 36057593, 2022). "Although the effect ARID1A/1B mutations found in neuroblastoma need to be functionally analyzed, the fact that Arid-1A and -1B are part of the SWI/SNF tumor suppressor complexes suggest that these factors are important for deregulation of neural crest cells and neuroblastoma development." (PMID 30760980, 2019). "Like CSS, ARID-1A and -1B mutations are also found in a subset of neuroblastoma." (PMID 30760980, 2019). "Taken together, these reports support and suggest a role for the 1p36 locus and ARID1A, in neuroblastoma tumor development, where loss of ARID1A modulates onset and invasiveness and induces a mesenchymal tumor phenotype that might increase resistance to chemotherapy." (PMID 34885007, 2021). "They contributed to failures of early stage treatment for NB patients and low survival rate to mutations of the two genes, suggesting ARID1A and ARID1B as contributors to neuroblastoma oncogenesis." (PMID 28055978, 2017). "Profiling in a panel of 11 neuroblastoma cell lines demonstrated circARID1A to be expressed throughout, but generally at lower levels than ARID1A mRNA." (PMID 37402719, 2023). "An essential circRNA derived from the ARID1A tumor suppressor gene was identified that uses the KHSRP RBP to promote neuroblastoma cell growth." (PMID 37402719, 2023). "MIB2 (skeletrophin) is a RING finger-dependent ubiquitin ligase first identified in a screen for genes that were upregulated by truncated ARID1A (SWI1) in neuroblastoma cells displaying increased cell–cell adhesions and aggregations." (PMID 35885948, 2022). "RNA-Seq of neuroblastoma cells after BAF disruption by silencing of ARID1A and ARID1B with two different shRNAs for each protein revealed the presence of hundreds of transcripts whose expression was modulated after the simultaneous knockdown of both subunits." (PMID 36057593, 2022). "In 2013, chromosomal deletions and sequence alterations of the chromatin-remodeling genes ARID1A and ARID1B were reported in 11% of neuroblastoma cases and were shown to be associated with decreased survival." (PMID 34200747, 2021). "Some well-known chromatin remodeling proteins include ARID1A/B and ATRX, which is one of the few known mutational targets in neuroblastoma." (PMID 34885007, 2021).
neuroblastoma (continued). "The most frequently harbored alterations of specific genes in neuroblastoma include heritable mutations in the ALK and PHOX2B observed in familial neuroblastoma, chromatin remodeling genes like ATRX, ARID1A and ARID1B and other important genes like PTPN11, MYCN, and NRAS." (PMID 37274289, 2023). "Indeed, deleterious mutations in the genes encoding the mSWI/SNF subunits ARID1A and ARID1B have been reported in neuroblastoma samples and are associated with poor patient prognosis." (PMID 36057593, 2022). "Neuroblastoma cells contain three main mSWI/SNF subtypes, but only BRG1-associated factor (BAF) complex disruption through silencing of its key structural subunits, ARID1A and ARID1B, impairs cell proliferation by promoting cell cycle blockade." (PMID 36057593, 2022). "ARID1A inactivation has also been found in pediatric neuroblastoma and aggressive meningioma." (PMID 35125107, 2022). "Overall, this work teased apart some of the challenges associated with understanding 1p36 loss of heterozygosity in MYCN-driven neuroblastoma, identifying the SWI/SNF chromatin remodeling complex subunit Arid1a as a MYCN collaborator that accelerates neuroblastoma onset." (PMID 34885007, 2021). "Thus, ARID1A now joins the list of candidate tumor suppressor genes present at 1p36 that have potential to impact on neuroblastoma initiation and progression." (PMID 34885007, 2021). "Similar to the mutations reported for ARID1A, truncating mutations have also been identified for ARID1B although in a lesser frequency and most of them associated with neurodevelopmental disorders or neuroblastomas." (PMID 31681423, 2019). "Interestingly ARID5A was among these 30 de novo mutant genes unique to Met2, and a recent sequencing study has reported that mutations in the chromatin-remodeling genes ARID1A and ARID1B in neuroblastoma were associated with a more aggressive phenotype." (PMID 24147068, 2013). "A proteomic analysis reveals SMARCC1, ARID1A and ARID1B are mainly related to chromatin remodeling in neuroblastoma." (PMID 41142119, 2025). "Structural disruption of the BAF complex, achieved by silencing of its essential subunits and direct SOX11 targets ARID1A and ARID1B, exerted an epigenomic reprogramming in neuroblastoma cells, resulting in reduced neuroblastoma invasiveness and metastasis." (PMID 36882421, 2023). "Previous genetic studies have identified candidate neuroblastoma tumor suppressor genes, including KIF1Bb, CHD5, miR-34a, ARID1A, and CAMTA1 located at 1p36." (PMID 34885007, 2021). "Among the eight relatively good prognostic markers, the neuroblastoma oncogenic roles of the highly-expressed LMO1 and the deletion of ARID1A have been evaluated." (PMID 28984200, 2017). "All described aberrations presented below – from chromothripsis to gene deletions, like ATRX, ARID1A and ARID1B genes – have, so far, only been described by sequencing methods of the neuroblastoma genome." (PMID 25161957, 2014). "Chromosomal deletions and sequence alterations in chromatin remodeling genes ARID1A and ARID1B were recently identified in 11% of neuroblastoma cases using massively parallel sequencing techniques." (PMID 24349301, 2013). "Transcriptomic analyses further allowed the authors to identify an adrenergic-to-mesenchymal transition, with neuroblastoma cells lacking ARID1A exhibiting an enriched mesenchymal gene signature." (PMID 34885007, 2021). "They further interrogated the role of ARID1A in human neuroblastoma cells, showing that genetic removal of ARID1A did not affect proliferation, but did promote cell invasion and migration." (PMID 34885007, 2021). "Interestingly, in the MYCN-amplified NGP neuroblastoma cell line, depletion of ARID1A using CRISPR-Cas9 promotes the transdifferentiation of NOR cells toward a MES state with increased invasion, migration, and resistance to cisplatin." (PMID 34200747, 2021).
neuroblastoma (continued). "Among the genes not previously known to be involved in neuroblastoma, deletions and sequence alterations of the chromatin-remodeling genes ARID1A and ARID1B were identified in 11% (8 of 71 tumors), and these aberrations correlated with a more aggressive phenotype." (PMID 25161957, 2014).